MORN4 (MORN repeat containing 4)
Description:
Plays a role in promoting axonal degeneration following neuronal injury by toxic insult or trauma.
Synonyms: C10orf83; bA548K23.4; FLJ25925; rtp; UTA
Tractability: PROTAC: its protein half-life has been measured.
Gene: Protein-coding gene on chromosome 10 (97,614,551 to 97,634,135, reverse strand). Ensembl gene ENSG00000171160.
Subcellular location: Cytoplasm; Cell projection, filopodium tip; Cell projection, stereocilium
Gene Ontology:
Molecular function: protein binding
Biological process: response to axon injury
Cellular component: cytoplasm; filopodium tip; stereocilium tip; actin-based cell projection; stereocilium
Genetic constraint (gnomAD): Loss-of-function variants: 7 observed, 13.96 expected, observed/expected ratio (o/e) 0.5, 90% interval 0.28 to 0.94. The upper end of that interval is the gene's LOEUF score, 0.94, which puts it in group 3 of 6, group 1 being the genes least tolerant of losing a copy. Missense variants: 151 observed, 185.17 expected, observed/expected ratio (o/e) 0.82, 90% interval 0.71 to 0.93. Synonymous variants: 52 observed, 70.64 expected, observed/expected ratio (o/e) 0.74, 90% interval 0.59 to 0.93.
Homologues: Orthologues: chimpanzee MORN4 (100% identical), dog MORN4 (99% identical), guinea pig MORN4 (98% identical), mouse Morn4 (98% identical), rabbit MORN4 (98% identical), pig MORN4 (96% identical), macaque MORN4 (86% identical), zebrafish morn4 (76% identical), tropical clawed frog MORN4 (68% identical), rat Morn4 (61% identical).
Diseases named in the same sentence as MORN4 in open-access papers:
MORN4 is named in the same sentence as 3 diseases in open-access papers, as found by Europe PMC text mining. Sharing a sentence is not in itself a finding about the gene and the disease. The quoted sentences say what the papers report.
cognitive decline (1 paper, 2021). "Furthermore, DMRs annotated to MORN4, AIRE, LY6G5C, and PRRT1 were identified for both rates of cognitive decline as measured by the slopes of mPACCdigit/mPACCtrailsB and CDR-SB." (PMID 34654479, 2021).
MORN4 also shares sentences with these, for which no sentence is quoted: breast carcinoma (1 paper); myocardial ischemia (1).